BRAF (B-Raf proto-oncogene, serine/threonine kinase)
Diseases named in the same sentence as BRAF in open-access papers (continued):
Sharing a sentence is not in itself a finding about the gene and the disease.
tumor (continued). "Compared with the non-mutated ones, the microenvironment of BRAF mutated tumors is characterized by a twice as high density of FOXP3+ Regulatory T cells (Tregs), which, by inhibiting the anti-tumor immune response, are associated with a poor prognosis." (PMID 31762942, 2019). "This demonstrated that BRAF V600E tumours were more likely to express multiple aggressive features when compared to RAS and tumours where no mutation was detected." (PMID 31623671, 2019). "Patient CRUK0056 was not a candidate to receive targeted therapies since her tumour was classified as stage IB and she did not harbour any mutation associated to known driver genes (e.g., EGFR, ALK, ROS1, BRAF, RET)." (PMID 31540260, 2019). "Further stratification using molecular markers, such as BRAF and KRAS mutations, and MSI status have been investigated with regard to their prognostic potential in this tumour group, but have not widely adopted to direct clinical management." (PMID 31775679, 2019). "As the combination of BRAF and MEK inhibitors showed increased efficacy against NGT41 in vitro, we next tested the antitumor activity of this combination therapy using orthotopic human tumor xenografts." (PMID 31345255, 2019). "Patients who did not meet the inclusion criteria, had no available tumor tissue or plasma samples (n = 13), and did not have BRAF assessment (n = 5) were excluded, leaving 407 patients for analysis." (PMID 31319569, 2019). "The AJCC‐UICC have included other prognostic factors such as degree of differentiation, R classification, circumferential resection margin, tumor regression score, CEA level, lymphovascular invasion, perineural invasion, microsatellite instability, KRAS, NRAS, and BRAF." (PMID 31069966, 2019). "In short, evidence suggests that BRAF mutation is not a reliable marker for differentiation of SSA/Ps from HPs and is unable to explain the biology of an SSA/P and its progression to neoplasia in its entirety." (PMID 31789933, 2019). "It should be highlighted that changes in the composition of tumor microenvironment resulting from treatment with BRAF-inhibitors are not persistent." (PMID 31762942, 2019). "Combination therapy with BRAF and MEK inhibitors has shown anti-tumor activity in ATC." (PMID 30863722, 2019). "Continuous signaling of MAPK maintains tumor growth, but BRAF activation alone is mostly not sufficient to drive their malignant behavior." (PMID 31181803, 2019). "Diagnostic tumour biopsy FFPE DNA was available for one of the ctDNA negative patients (P67), and ddPCR analysis did not confirm the BRAF p.V600E detected by Sanger (802 wildtype copies detected, 0 mutant copies detected)." (PMID 31767937, 2019). "Only one patient without baseline mutations in ctDNA nor tumor tissue gained mutations in KRAS, NRAS, and BRAF at progression in ctDNA." (PMID 31350822, 2019). "Consequently, BRAF or MEK1/2 inhibitors are synthetic lethal with the MCL1 inhibitor AZD5991, driving profound tumour cell death that requires BAK/BAX, BIM and BMF, and inhibiting tumour growth in vivo." (PMID 31727888, 2019). "Tumor genetic defects in USP8, GNAS, USP48 and BRAF are some of the commonly encountered tissue-specific changes and may explain a larger percentage of the developed tumors." (PMID 31877737, 2019). "Thus, in the present study, the role of prolonged leptin exposure in tumor progression and/or expansion, as it may occur in vivo in TC patients with high BMIs, was first analyzed in two PTC-derived cell lines carrying RET/PTC1 (TPC-1) and BRAF (K1) mutations which both express OB-R." (PMID 30906321, 2019). "In patients without treatment benefit (n = 13), four BRAF p.V600E mutations and one rare KRAS p.G60D mutation were detected in tumor tissue." (PMID 31350822, 2019).
tumor (continued). "RET/PTC-positive samples were associated (not statistically significant) with a higher rate of tumor growth (mostly T3/T4 classification), more frequent extrathyroidal extension, intravascular invasion and multifocality compared to BRAF-positive samples." (PMID 31085772, 2019). "In the current work, we have shown that β-sitosterol has a particular effect on BRAF-driven tumors, but this does not exclude an action of β-sitosterol on other biological processes in tumor cells." (PMID 30971321, 2019). "Notably, we have observed PSCs in all tumor cell lines examined to date, including A375 melanoma cells carrying the BRAFV600E oncogene (where BRAF depletion disrupted PSC formation) as well as cancer cells such as HeLa that lack known RAS pathway mutations." (PMID 31106232, 2019). "Secondly, data on EGFR mutational status was only available for 42 (77.8%) patients and no data was available on other tumor mutations (e.g. ALK, ROS1, BRAF) for which targeted treatments now exist." (PMID 30973926, 2019). "Tumor molecular profiling was retrieved from clinical documentation when available: 62% (n = 44/71) were KRAS mutant, 3% (n = 2/58) NRAS mutant, 4% (n = 3/68) BRAF mutant and 20% (n = 6/30) HER2 amplified." (PMID 31355139, 2019). "Additionally, an analysis of the correlation network reconstructed using TCGA-SKCM emphasized KMO and KYNU with high variability among BRAF wild-type compared with V600E, which underscored their role in distinct CD4+ T-cell behavior in tumour immunity." (PMID 31434983, 2019). "A common reason is that in populations with EGFR, BRAF, MET, ALK and other gene mutations, it is not easy to produce new antigens of tumours, and the tumour mutation load is lower." (PMID 30862891, 2019). "The tumour was MSI-H, MLH1 and PMS2 deficient, and negative for BRAF V600E, but no pathogenic mutation was identified on next generation sequencing." (PMID 31647837, 2019). "Additional factors considered in the adjustment model, comprising tumor colorectal subsite location, smoking history, BMI, and mutations of KRAS, NRAS, BRAF, and PIK3CA, did not meet the 10% change in coefficient criteria for confounder selection." (PMID 31367996, 2019). "Specifically, tumours with both BRAF mutation and MITF activation were more sensitive to PLX4720 than tumours with BRAF mutation without MITF activation." (PMID 29950679, 2018). "In conclusion, this study demonstrated that evaluation with the Idylla system of the BRAF and NRAS mutation status in cfDNA may be a surrogate for determination of the BRAF and NRAS status in tumor tissue." (PMID 30546839, 2018). "The kinase-dead BRAF(ΔNVTAP/V471F)-induced foci formation in vitro and tumor formation in vivo even in the absence of active RAS, but dependent on endogenous RAF molecules." (PMID 29930381, 2018). "The precise role of BRAF and NRAS mutations in tumour progression has not yet been definitively established." (PMID 29755118, 2018). "These tumours do not harbour mutations in the IDH, BRAF or histone genes, but instead are characterised by MYBL gene rearrangements, which are thought to be driver mutations." (PMID 29098416, 2018). "It should be highlighted that the LOD of Sanger sequencing for mutations of both BRAF and KRAS genes at their laboratory and the estimation of tumor cell percentage were not mentioned." (PMID 29879227, 2018). "Responses were irrespective of tumor RAS and BRAF mutational status, immune cell PD-L1 expression or clinical history of LS." (PMID 34532592, 2018). "BRAF mutation is a strong negative prognostic biomarker and evidence is accumulating that patients with a BRAF mutant tumor do not benefit from anti-EGFR therapy." (PMID 29755687, 2018).
tumor (continued). "Thus, if the sample contains only a few tumor cells IHC is the preferred approach (for example for evaluation of the ALK and BRAF V600E status)." (PMID 29534030, 2018). "The risk of disease recurrence following a negative SLNB was increased for patients with either a BRAF or NRAS mutant tumour compared to wild-type tumours (aHR 1.92, 95% CI: 1.02–3.60, p = 0.04)." (PMID 29755118, 2018). "Although canine MM would likely be unresponsive to this BRAF kinase inhibitor, since the ortholog to the V600E mutant is not a frequent event in this tumor type, the rational targeting of the BRAF mutant is validated in canine cancer." (PMID 29385676, 2018). "With no significant proteins intersecting between the two tumor types, no cross-cancer effect can be identified for BRAF." (PMID 30442178, 2018). "The MARTHA trial was conducted in a pre-RAS/BRAF era and data on RAS/BRAF mutational status were largely lacking, thus we were not able to analyze tumor sidedness effect in the wild type patient subpopulation." (PMID 29416820, 2018). "When MSI-positive and ultramutator tumours were excluded from the Australian analysis, KRAS mutation was significantly associated with prognosis, but BRAF mutation was not." (PMID 30042065, 2018). "However, recent studies showed that different BRAF fusions, such as GTF2I-BRAF, DGKI-BRAF, and TMEM106B-BRAF, activated the MAPK pathway, thereby regulating tumor growth in multiple cancers." (PMID 30111351, 2018). "Collectively, our data suggest that miR-550a-3-5p acts as a tumor suppressor through the targeting of oncogenic YAP and may be a new therapeutic tool for YAP-mediated BRAF inhibitor resistance in BRAF-mutant cancer cells." (PMID 29844307, 2018). "These genetic alterations involving BRAF, KRAS, RAF1, NF1, FGFR1, and FGFR2 were mutually exclusive (i.e. no tumor harbored any two of these variants simultaneously)." (PMID 29880043, 2018). "Single KO of either CRAF or BRAF was not sufficient to prevent malignant tumour growth and maintenance in vivo and cell proliferation in vitro." (PMID 28497782, 2017). "RhoJ deletion significantly inhibited the growth of melanoma tumors that expressed either no PTEN (p<0.0001, Log-rank) or had one functional copy of PTEN (p<0.0001, Log-rank), suggesting that RhoJ drives tumor growth by amplifying BRAF and not AKT signaling." (PMID 28753606, 2017). "Combinations of BRAF and MEK inhibitors have therefore been used to induce deeper suppression of MAPK signaling in the BRAF mutant disease setting to preempt MAPK-pathway reactivation and tumor escape." (PMID 28982154, 2017). "We showed that systemic expression of HGF via AAV-HGF treatment failed to promote resistance to BRAF inhibition in G361 tumor xenografts, whereas local/tumor doxycycline–induced expression of HGF was capable of conferring resistance." (PMID 28147313, 2017). "Local/tumor HGF expression conveyed a significant rescue of C-1 driven tumor growth inhibition (P < 0.001), suggesting local HGF expression may be required to mediate BRAF inhibitor resistance." (PMID 28147313, 2017). "AXIN2+DKK1 methylation significantly predicted recurrence independent of age, sex, tumor size, localization, differentiation, CIMP, BRAF and KRAS mutations." (PMID 28368388, 2017). "However, BRAF inhibitors were reperted to accelerated skin tumors and soft agar colonies in DMBA/TPA tumor induction." (PMID 28865485, 2017).
tumor (continued). "The nodular subtype was more common in BRAF- and NRAS-mutant groups, while there were no major differences regarding other histologic risk factors such as tumor depth or presence of ulceration." (PMID 28797232, 2017). "Enhanced inhibition of ERK pathway by combination treatment such as BRAF and MEK inhibitors could induce more cell death and plus with the change in tumor microenvironment may affect to tumor progression." (PMID 28830513, 2017). "Regorafenib is a potent oral inhibitor of multiple kinases which might be involved in tumor angiogenesis (VEGFR-1, -2, -3, Tie-2), oncogenesis (KIT, RET, RAF-1, BRAF, BRAFV600E), and tumor niche formation (PGDFR, FGFR)." (PMID 29371921, 2017). "BRAFV600E positive cancer cell lines that express higher levels of MAP3K8 tended to be less sensitive to BRAF inhibitor drugs; MAP3K8 expression increased in the tumours of patients treated with BRAF inhibitors, and was even further elevated in drug resistance relapse tumour samples." (PMID 28282860, 2017). "One mechanism is ERK negative feedback on RAS: Treatment with BRAF inhibitors arrests tumor growth by inhibiting the ERK pathway." (PMID 29100459, 2017). "A high intra-tumor copy number variation of NRAS/chromosome 1 was observed in 25% (8/32) of BRAF/NRAS WT, 30% (9/30) of HET and 23.8% (5/21) of High non-HET." (PMID 28668077, 2017). "It is important to note that these biomarkers are not uniformly distributed by stage, with MSI-H tumours associated with lower stage (21% in stage II vs 14% stage III and 4% stage IV), and BRAF mutant tumours more likely to occur at a higher stage." (PMID 28390415, 2017). "Furthermore, BRAF inhibitor can increase intratumoral infiltration and antitumor activity of TCR-engineered ACT by inhibiting tumor cell production of the vascular endothelial growth factor (VEGF) in xenograft mouse model." (PMID 29156850, 2017). "Our results showed an increasing trend of BRAF and a decreasing trend of RET/PTC prevalence over time in PTCs and classical PTCs, accompanied by an older age of PTC patients, an increase in proportion of PTMC and less aggressive behaviours of tumours." (PMID 27793009, 2017). "Because on BRAF inhibitor monotherapy tumour growth had resumed despite ERK being still inhibited, we wanted to see whether these MITF‐high tumours are enriched for AXL‐high cell populations." (PMID 28606996, 2017). "In conclusion, our data established that LY3009120, a selective panRAF inhibitor, is superior to previously investigated selective BRAF inhibition in preclinical models of human CRC, as it potently inhibited proliferation and tumor growth in the BRAFmut and KRASmut subtypes." (PMID 27999210, 2017). "When MLH1 and PMS2 are absent by IHC, the next step is analysis of BRAF by either PCR or IHC to help determine if the patient has a sporadic tumor or should be further evaluated for LS." (PMID 28259170, 2017). "Of the patients who did not experience a clinical benefit, three carried BRAF mutations, and one carried BRAF/PIK3CA mutations in their tumor tissues prior to treatment." (PMID 27852040, 2017). "One limitation of the present study is that the primary tumor site and RAS/v-Raf murine sarcoma viral oncogene homolog B1 (BRAF) mutation were not included in subgroup analysis because of the small sample size." (PMID 29273089, 2017). "One study proposed that mutant BRAF had no impact on the disease-free interval from diagnosis of the culprit tumor to first distant metastasis." (PMID 28797232, 2017). "In this model, the BRAF inhibitor did not increase the tumor immunogenicity, but it favored the recruitment of CD8 and natural killer cells." (PMID 27974353, 2017).
tumor (continued). "So far, the development of targeted therapies was mostly fueled by knowledge related to primary tumor biology and, currently, around one dozen therapeutic antibodies and 28 different inhibitors are in clinical application, targeting essentially the tumor antigens HER2, EGFR, EpCAM, BRAF and VEGF." (PMID 27683128, 2017). "Markers of favorable prognosis: hypermutated tumor phenotype; MSI-H, especially in the absence of early onset of the disease and mutations in BRAF gene; CIMP-H in combination with MSI; proximal localization of CIMP-H tumors." (PMID 27276710, 2016). "All the up-regulated miRNAs show increased expression in BRAF V600E positive tumor samples compared to BRAF V600E negative tumor samples, except miR-34a-5p, miR-182-5p and miR-183-5p." (PMID 27248468, 2016). "The incidence of AEs was similar regardless of tumour RAS/BRAF status, and no new safety signals were noted in these analyses." (PMID 27764839, 2016). "ZEB1 knockdown alone was as efficient as vemurafenib treatment in decreasing SKMEL5 xenografted tumor growth, but the combined inhibition of BRAF and ZEB1 did not lead to a further significant decrease in tumor growth (Fig EV4D)." (PMID 27596438, 2016). "The BRAF inhibitor vemurafenib for example, was tested in a series of non-melanoma tumours including NSCLC." (PMID 27350784, 2016). "Other studies support that Akt, a member of the PI3K/Akt/MTOR pathway, could also drive tumor resistance to BRAFV600E inhibitors and thus simultaneous inhibition of those two pathways (BRAF and PI3K) is needed." (PMID 26802026, 2016). "In this latter tumor, we have found that ACKR2 expression is downregulated in more aggressive tumors by the activation of the KRAS/BRAF/ERK pathway, thus unleashing chemokine-mediated macrophage recruitment and their acquisition of an M2-like phenotype that sustains angiogenesis and tumor growth." (PMID 28123388, 2016). "Concerning follicular thyroid lesions, BRAF V600E is virtually absent in this tumor subtype and the most common MAPK-pathway alteration is the presence of RAS mutations." (PMID 27127508, 2016). "Our initial limited “targeted” analyses of PTEN, KRAS, BRAF, PI3KCA and MET did not elucidate predictors of response to MEK inhibitors with any tumor-specific genetic variants." (PMID 26683364, 2016). "The fact that these organoids have not progressed beyond the initial hit in the BRAF gene, yet, allowed the elucidation of early events in the serrated neoplasia pathway." (PMID 27221051, 2016). "As a result, we found that reduced NDRG4 mRNA expression was associated with tumor progression, as well as unfavorable outcome independent of patients' clinical features and molecular variables including KRAS, BRAF and PIK3CA mutations and MSI status." (PMID 26515606, 2016). "Regarding the role of BRAF mRNA expression in wild-type PTC, the issue of tumor heterogeneity may have little impact on the aggressive clinicopathological characteristics." (PMID 27410688, 2016). "However, only approximately 40 % of CRC patients with tumours wild-type for KRAS, NRAS and BRAF benefit from such therapy, and patients who initially respond eventually become resistant to these drugs." (PMID 27160084, 2016). "The roles of the wild-type BRAF and BRAFV600E in tumor progression are apparently complex." (PMID 27410688, 2016). "Similarly, the MKK2[Q60P] was found in tumor cells with sustained MAPK activation and resistance to BRAF and MEK inhibitors." (PMID 27303665, 2016). "Cluster three, which contained expressed mutations in BRAF (K601E) and MSH6 (nonsense), made up 92% of the baseline tumour, but was absent in the post-treatment samples, suggesting that it harboured enhanced susceptibility to oestrogen deprivation." (PMID 27502118, 2016). "Interestingly, gamitrinib inhibited foci and colony formation in both tumor cell lines, with BRAF-V600E HT29 cells treated with gamitrinib showing a significantly lower colony/foci forming ability compared to BRAF-wt HCT116 cells." (PMID 26084290, 2015).